CRP (C-reactive protein)
Diseases named in the same sentence as CRP in open-access papers (continued):
Sharing a sentence is not in itself a finding about the gene and the disease.
diverticulitis (continued). "According to the WSES classification, the complicated diverticulitis group exhibited significantly elevated levels of CRP, WBC, neutrophil count, neutrophil percentage, procalcitonin, and direct bilirubin in comparison to the non-complicated group." (PMID 40387926, 2025). "In contrast, high C-reactive protein values have been repeatedly identified as good predictors for complicated diverticulitis with more severe outcomes." (PMID 39766542, 2024). "Only significantly higher serum levels of CRP before operation were found in the perforated MD group than diverticulitis group." (PMID 38291433, 2024). "Procalcitonin had been shown to have better specificity and sensitivity than CRP, especially in segregating out complicated from uncomplicated diverticulitis." (PMID 37760703, 2023). "The AUC value of the MDW for complicated diverticulitis was higher than those of other inflammatory biomarkers—CRP (0.800), NLR (0.724), WBC (0.679), and PLR (0.662)." (PMID 36977993, 2023). "Biomarkers such as CRP and calprotectin have thus far only demonstrated limited specificity and sensitivity in the management of diverticulitis." (PMID 37760703, 2023). "On admission, CRP is the most useful inflammatory marker in daily practice for the severity prediction of acute diverticulitis." (PMID 36176861, 2022). "CRP is the most useful inflammatory marker in daily practice for the severity of acute diverticulitis as well as the qSOFA score." (PMID 36176861, 2022). "C-reactive protein > 170 mg/L represents the cut-off point between moderate and severe diverticulitis, and a CT scan is mandatory." (PMID 36176861, 2022). "CRP ≥150 mg/L is an incriminating factor with strong possibility for perforated diverticulitis, especially in advanced age, and a CT scan is required necessarily." (PMID 36176861, 2022). "CRP > 50 mg/L indicates uncomplicated acute diverticulitis, but CRP > 170 mg/L represents the cut-off point between moderate and severe diverticulitis." (PMID 36176861, 2022). "The authors concluded that CRP is a useful tool in the prediction of the clinical severity of acute diverticulitis." (PMID 32381121, 2020). "The study confirmed that CRP is useful for predicting the severity of acute diverticulitis on admission." (PMID 32381121, 2020). "The median CRP in patients with complicated diverticulitis was significantly higher than in patients with uncomplicated disease (224 mg/l, range 99–284, vs. 87 mg/l, range 48–151, respectively)." (PMID 32381121, 2020). "There are reports that patients with acute complicated diverticulitis present with considerably higher CRP levels compared with patients with uncomplicated episodes." (PMID 29091955, 2017). "The overall mean CRP among patients with uncomplicated diverticulitis was 68 mg/L with a range of 25 to 96 mg/L." (PMID 28799055, 2017). "This systematic review found that CRP, WBC count, and clinical signs (constipation, generalized abdominal pain, and vomiting) are risk factors for complicated diverticulitis." (PMID 28799055, 2017). "Three studies calculated the optimal threshold value of CRP level to distinguish uncomplicated from complicated diverticulitis." (PMID 28799055, 2017). "CRP cut-off value of 149.5 mg/l significantly discriminated acute uncomplicated diverticulitis from complicated diverticulitis (specificity 65 %, sensitivity 85 %, area under the curve 0.811, p = 0.0001)." (PMID 27478494, 2016). "The study confirmed that CRP is useful for the predicting the severity of acute diverticulitis on admission." (PMID 27478494, 2016). "The author concluded that CRP is a useful tool in the prediction of the clinical severity of acute diverticulitis." (PMID 27478494, 2016). "The median CRP in patients with complicated diverticulitis was significantly higher than in patients with uncomplicated disease (224 mg/l, range 99–284 vs 87 mg/l, range 48–151)." (PMID 27478494, 2016).
diverticulitis (continued). "A CRP cutoff value of 170 mg/L significantly discriminated severe from mild diverticulitis (87.5 % sensitivity, 91.1 % specificity, area under the curve 0.942, P < 0.00001)." (PMID 27478494, 2016). "The two groups were comparable with respect to age, sex, previous diagnosis of diverticulosis, previous episodes of diverticulitis, duration of symptoms before admission, and CRP/WBC at admission." (PMID 24078823, 2013). "In our study, we evaluated the predictive value of baseline serum sodium levels, along with inflammatory markers such as WBC count and CRP levels, in differentiating complicated from uncomplicated diverticulitis in patients hospitalized and followed up for acute diverticulitis." (PMID 40282883, 2025). "In univariate logistic regression analysis, it showed that age, HTN, DM, left-sided diverticulitis, mHG, lymphocytes, WLR, NLR, PLR, CRP levels, CRP/albumin ratio, and mGPS were markedly associated with the non-operative treatment failure for diverticulitis." (PMID 36927780, 2023). "Based on the available data, CRP appears to be the most useful biomarker for diverticulitis." (PMID 36978310, 2023). "Moreover, although within normal value range, a relatively elevated CRP (p = 0.009) was obtained for obstruction and diverticulitis compared to bleeding/others group." (PMID 35053658, 2022). "The use of the CRP test is only recommended for patients with acute LRTIs or diverticulitis." (PMID 31455104, 2019). "However, CRP levels are only helpful as an indicator for the presence of complicated diverticulitis." (PMID 29091955, 2017). "Furthermore, the analyses proved CRP to be the most valuable initial laboratory test in the differentiation of acute diverticulitis from other acute abdominal conditions." (PMID 27613727, 2017). "A repeated CT scan may be omitted in patients with clinical recurrent disease and a previously documented history of diverticulitis, especially with C-reactive protein (CRP) <50 mg/mL." (PMID 27613727, 2017). "Patients with a CRP of 25 mg/l had a 15 % chance of having complicated diverticulitis." (PMID 27478494, 2016). "However, the study found that the median values of CRP in patients with uncomplicated diverticulitis increased significantly during the 25 years, both for values measured at admission as well as for the maximum measured values during the hospital stay." (PMID 24802814, 2014). "We also noted a strong (but statistically non-significant) association between previous uncomplicated diverticulitis and mild-moderately raised inflammatory markers (CRP 100–200 mg/L) with a subsequent CRC diagnosis (OR 3.08, P = 0.112) and (OR 3.31, P = 0.069) respectively." (PMID 40088275, 2025). "CRP varies with the severity of the diverticulitis and may aid to predict perforation." (PMID 24802814, 2014). "Only one study compared MDW with CRP level and WBC count and concluded that MDW more accurately identified complicated diverticulitis." (PMID 41184833, 2025). "Age, white blood cell (WBC) count, neutrophil count, C-reactive protein (CRP) level, neutrophil-to-lymphocyte ratio (NLR), platelet-to-lymphocyte ratio (PLR), and MDW were significantly higher in the complicated diverticulitis group (p < 0.05)." (PMID 36977993, 2023). "Guidelines from the Dutch Royal College of GPs recommend the use of CRP POC tests for the management of adults with cough, suspected diverticulitis, and exacerbation of COPD." (PMID 36823597, 2023). "They concluded that the NLR was more accurate than CRP levels, and WBC and neutrophil counts in predicting the need for a surgical intervention, which indicates complicated diverticulitis." (PMID 29091955, 2017). "Several studies have attempted to calculate the optimal threshold for the WBC count and CRP level in distinguishing complicated diverticulitis from simple diverticulitis; however, so far, no consensus has been reached." (PMID 36977993, 2023).
diverticulitis (continued). "In addition to the WBC count and CRP level, two easily accessible hemogram-derived parameters, namely the NLR and PLR, have been used to predict complicated diverticulitis." (PMID 36977993, 2023). "When the same variables were compared for the severity of colonic diverticulosis, it was observed that HDL cholesterol was lower in more severe forms of diverticulosis (DICA category 2 and 3), while CRP and ALP levels were significantly higher (p = 0.006, p = 0.015, and p = 0.029, respectively)." (PMID 35056346, 2021). "We expected to find that CRP and WBC count were related to complicated diverticulitis." (PMID 28799055, 2017). "We propose a prognostic model in which the following parameters will be included: first episode of diverticulitis, vomiting, constipation, diffuse abdominal pain, rebound tenderness, défense musculaire (as a clinical sign of peritonitis), comorbidity (ASA > I), steroid usage, and CRP level." (PMID 28799055, 2017). "Although high-level evidence is lacking, this study demonstrates that CRP level, WBC count, clinical signs (generalized abdominal pain, constipation, vomiting), steroid use, number of episodes, and comorbidity are risk factors for complicated diverticulitis." (PMID 28799055, 2017). "Serum inflammation markers, such as C-reactive protein (CRP) levels, white blood cell (WBC) count, and neutrophil-to-lymphocyte ratios (NLR), may help to differentiate severity of acute diverticulitis and predict the need for surgical intervention in clinical practice." (PMID 29091955, 2017). "Thus, a low CRP does not exclude complicated diverticulitis." (PMID 35063008, 2022). "Elevated plasma CRP (>10 mg/L) was found in 5 of 42 patients, which included 4 patients with IBD and a single non-IBD patient with diverticulitis." (PMID 35060938, 2022).
liver failure (52 papers, 2009 to 2025). A liver disease characterized by the liver losing or has lost all of its function. "The independent risk factors (history of ulcer disease, HB, PLT, ALB, heart rate, SBP, liver failure, CRP) screened-out by the multivariate logistic risk regression model were ranked according to their importance by machine learning using R language." (PMID 41585275, 2025). "Increased CRP levels are typically associated with disease, but liver failure is one condition observed to impair CRP production." (PMID 29706967, 2018). "Increases in CRP levels have been associated with liver failure." (PMID 38610862, 2024). "Moreover, several studies have also demonstrated that more severe liver failure is associated with lower CRP levels." (PMID 29041907, 2017). "The ranking assigned by the new prediction model in the order of high to low was as follows: history of ulcer disease > PLT > Liver failure > HB > Heart rate > CRP > SBP > ALB." (PMID 41585275, 2025). "All parameters were altered, with very high levels of acute markers of inflammation, such as CRP, ferritin, and D-dimer, together with kidney and liver failure markers (all, p < 0.042)." (PMID 37405379, 2023). "CRP levels increased at three months in all four cases except one case where the patient died of progressing liver failure at four months of rifaximin administration." (PMID 36983211, 2023). "As most CRP components are synthesized in the liver, liver failure would hinder the production of CRP." (PMID 35204599, 2022). "This agrees with frequently impaired CRP production in liver failure with increased bilirubin values." (PMID 35082693, 2021). "Further, additional laboratory parameters such as creatinine, transaminases, and C-reactive protein (CRP) levels are helpful to control potential influencing conditions such as renal and hepatic failure or inflammations." (PMID 28042579, 2016). "A similar case with regard to dissociation between IL18 and CRP as well as IL6 was reported in which a patient was suffered from progressive liver failure requiring liver transplantation in the relapse of AOSD." (PMID 24455384, 2013). "This may be attributed to CRP’s hepatic origin - in liver failure, compromised synthetic function appears to reduce CRP production." (PMID 40761850, 2025). "A significant increase of SGOT, SGPT, and CRP levels can be an indicator of liver failure." (PMID 39044209, 2024). "Also, it was discussed that even if CRP levels were related to various medical conditions, liver failure and certain medications affect CRP production." (PMID 37873776, 2023). "Moreover, even though elevated CRP levels are related to various medical conditions, liver failure and the administration of certain drugs affect CRP production." (PMID 37873776, 2023). "Our data also support that the CRP in exosomes secreted by PD-MSC transplantation is a trigger as a positive effector to regenerate damaged liver via activated angiogenesis in a rat model with hepatic failure." (PMID 33133194, 2020). "It is known that severe liver failure might lower the CRP value, but only little information is available in literature." (PMID 32434519, 2020). "Because CRP is synthesized in the liver, it may be interesting to study its production in hepatic failure, a frequently observed disease in ICU patients, which shares some clinical aspects with the septic process." (PMID 24286072, 2013). "Therefore, the objectives of this study were to compare the expression of CRP in exosomes of a hepatic failure rat model (bile duct ligation, BDL) and to evaluate the therapeutic effect by their correlation between CRP and angiogenesis depending on PD-MSC transplantation." (PMID 33133194, 2020). "During liver failure, aptamer targets TNF and CRP mainly by inhibiting TNF and tracking the site of CRP secretion, thereby blocking the inflammatory process and reducing and eliminating inflammation." (PMID 38305844, 2024).
liver failure (continued). "Second, an exaggerated hyperinflammatory response from significantly elevated C-reactive protein (CRP), LDH, ferritin, and IL-6 levels contributes to liver injury or even develops into liver failure in critically ill patients." (PMID 35464491, 2022). "All the parameters were abnormal, with very high levels of CRP and PCT (as acute markers of inflammation and infection), while the markers for renal and hepatic insufficiency, as well as metabolic acidemia, were also very high." (PMID 31064391, 2019). "C-reactive protein (CRP) is a pentameric protein that is present in the bloodstream during inflammatory events, e.g., liver failure, leukemia, and/or bacterial infection." (PMID 27708384, 2016). "Some cases without CRP response in our cohort presented with a very fulminant course and hepatic failure, which was similar to a finding in a previous study." (PMID 26259626, 2015). "Liver failure impairs CRP production, but no other intercurrent pathologies and very few drugs reduce CRP values unless they also affect the underlying pathology providing the acute-phase stimulus." (PMID 24778096, 2014). "Conversely, a lack of C-reactive protein elevation in inflammation may be seen with hepatic failure, as well as during flares of conditions such as SLE." (PMID 30538987, 2018). "The lower CRP in non-survivors, on the other hand, might indicate immune exhaustion or liver failure, with a failing attempt to bring about an effective response in order to establish control of their acute illness." (PMID 24716510, 2014). "In addition to high CRP levels, D-dimer could serve as a new biomarker for acute-onchronic liver failure (ACLF) syndrome and to evaluate deterioration and short-term mortality in patients with liver failure due to HBV." (PMID 35223421, 2021).
rectal cancer (52 papers, 2005 to 2025). A primary or metastatic malignant neoplasm that affects the rectum. "Previous studies have revealed pre-therapeutic elevated CRP to be significantly associated with the response to CRT for patients who received NACRT followed by surgery for rectal cancer." (PMID 40615597, 2025). "Similar to these reports, a high level (> 3.3 mg/L) of CRP was associated with an increased risk of CVD in rectal cancer patients." (PMID 38074681, 2023). "The results showed that CRP remained a risk factor for CVD in patients with rectal cancer (OR: 2.411, 95% CI: 1.378-4.165, p=0.002)." (PMID 38074681, 2023). "The results found that increased CRP was significantly associated with CVD in rectal cancer patients (OR: 2.767, 95% CI 1.646-4.592, p < 0.001)." (PMID 38074681, 2023). "The results obviously indicated that CRP served as an independent risk factor for CVD in patients with rectal cancer after adjusting for potential confounding factors." (PMID 38074681, 2023). "In our research, we have found that CRP levels are linked to CVD in rectal cancer patients, and that chemotherapy-induced higher CRP levels are known to affect the vascular endothelium in cardiovascular disease." (PMID 38074681, 2023). "The results consistently demonstrated that CRP was considered as an independent risk factor for CVD in patients with rectal cancer." (PMID 38074681, 2023). "Our findings demonstrated that the lower expression of CRP levels seem to be independently associated with response and prognosis to treatment in patients with locally advanced rectal cancer who underwent long course nCRT." (PMID 35158759, 2022). "The association of C-reactive protein with the prediction of survival and treatment response in rectal cancer has been examined in several prospective studies." (PMID 34321074, 2021). "Further analysis reveals that the -286 SNP mutations of CRP tend to co-occur with mutated APC particularly in rectal cancer (p = 0.04; n = 67)." (PMID 25025473, 2014). "Additionally, the ability of the model to predict CVD in patients with rectal cancer was improved by adding CRP, further highlighting the value of CRP in predicting CVD risk." (PMID 38074681, 2023). "Also, elevated CRP was found associated with poor outcomes after chemoradiotherapy and surgery for rectal cancer." (PMID 34321074, 2021). "If the present findings are replicated in future studies, determination of the pre-treatment plasma CRP level may help to obtain a more precise individual risk profile and contribute to the tailored treatment of rectal cancer patients." (PMID 33023215, 2020). "The aim of the present study was to investigate the association of the pre-treatment C-reactive protein (CRP) plasma level with survival outcomes in a cohort of 423 consecutive patients with locally advanced rectal cancer treated with neo-adjuvant radiochemotherapy followed by surgical resection." (PMID 33023215, 2020). "Elevated CRP and WBC have been widely recognized as markers of systemic inflammation and have been associated with poorer oncological outcomes in rectal cancer patients." (PMID 40277783, 2025). "While our study focused on the prognostic value of NLR, PLR, and CEA, previous research has identified other serum biomarkers, including IL-6, TNF-αR2, adiponectin, and C-reactive protein as potential indicators of prognosis in rectal cancer." (PMID 41154438, 2025). "Several studies have demonstrated that systemic inflammatory markers, such as CRP, neutrophil-to-lymphocyte ratio (NLR), and platelet-to-lymphocyte ratio (PLR), are associated with poor prognosis in rectal cancer." (PMID 40277783, 2025). "This retrospective cohort study aimed to assess the predictive value of early postoperative C-reactive protein (CRP) levels for complications following robot-assisted rectal surgery (RARS) for rectal cancer." (PMID 40877485, 2025).